ECHDC2 (enoyl-CoA hydratase domain containing 2)
Synonyms: FLJ10948
Tractability: PROTAC: its protein half-life has been measured.
Gene: Protein-coding gene on chromosome 1 (52,895,910 to 52,927,212, reverse strand). Ensembl gene ENSG00000121310.
Subcellular location: Mitochondrion
Subcellular location (Human Protein Atlas): Mitochondria
Gene Ontology:
Molecular function: enoyl-CoA hydratase activity; catalytic activity; RNA binding
Biological process: fatty acid beta-oxidation; branched-chain amino acid catabolic process; L-amino acid catabolic process
Cellular component: mitochondrion
Genetic constraint (gnomAD): Loss-of-function variants: 27 observed, 36.05 expected, observed/expected ratio (o/e) 0.75, 90% interval 0.55 to 1.03. The upper end of that interval is the gene's LOEUF score, 1.03, which puts it in group 4 of 6, group 1 being the genes least tolerant of losing a copy. Missense variants: 309 observed, 348.56 expected, observed/expected ratio (o/e) 0.89, 90% interval 0.81 to 0.97. Synonymous variants: 136 observed, 143.14 expected, observed/expected ratio (o/e) 0.95, 90% interval 0.83 to 1.1.
Homologues: Orthologues: chimpanzee ECHDC2 (99% identical), macaque ECHDC2 (97% identical), guinea pig ECHDC2 (88% identical), rat Echdc2 (87% identical), dog ECHDC2 (86% identical), mouse Echdc2 (86% identical), rabbit ECHDC2 (82% identical), pig ECHDC2 (73% identical), tropical clawed frog echdc2 (66% identical), zebrafish echdc2 (63% identical), Drosophila melanogaster CG8778 (53% identical), Caenorhabditis elegans ech-5 (47% identical), and 7 more. Paralogues in human: AUH (53% identical), ECHS1 (33% identical), ECH1 (31% identical), CDYL2 (27% identical), HIBCH (27% identical), ECHDC3 (26% identical), CDYL (26% identical), ECHDC1 (24% identical), CDY2A (23% identical), CDY2B (23% identical), CDY1B (23% identical), CDY1 (22% identical), and 1 more.
Diseases named in the same sentence as ECHDC2 in open-access papers:
ECHDC2 is named in the same sentence as 11 diseases in open-access papers, as found by Europe PMC text mining. Sharing a sentence is not in itself a finding about the gene and the disease. The quoted sentences say what the papers report.
breast adenocarcinoma (1 paper, 2024). "SCP2 was also involved in recurrent fusions with ECHDC2 and FAF1 in breast adenocarcinomas." (PMID 39038933, 2024).
myocardial ischemia (1 paper, 2016). A disorder of cardiac function caused by insufficient blood flow to the muscle tissue of the heart. "The ECHDC3 role in CVD is scarcely explored to allow a more comparative discussion of our data, but is known that ECHDC2 upregulation in cardiac tissue of rats was related to increased susceptibility to myocardial ischemia/reperfusion injury." (PMID 27586541, 2016).
oropharyngeal cancers (1 paper, 2019). Carcinoma, predominantly squamous cell, arising from the epithelial cells of the oropharynx. "A distinct set of prognosticators were identified for HPV+ and HPV- oropharyngeal cancers; ECHDC2, GGT6, HERC5 were showed to be associated with HPV+; HERC5 has a known anti-viral activity and its possible role in HNSCC HPV associated cancer is yet to be studied." (PMID 31310629, 2019).
sarcopenia (1 paper, 2024). Progressive decline in muscle mass due to aging which results in decreased functional capacity of muscles. "Consistently across the three outcomes, RXRA, MDM1, RBL2, KCNJ2, and ADHFE1 were identified as risk factors, while NMB, TECPR2, MGAT3, ECHDC2, and GINM1 were identified as protective factors, all with potential as biomarkers for sarcopenia progression." (PMID 39409102, 2024).
tumor (3 papers, 2021 to 2026). "Enrichment analyses demonstrated that ECHDC2 is involved in tumor progression, with a particular focus on the PI3K/Akt signaling pathway." (PMID 41732157, 2026). "The results showed the tumor sizes and weights of ECHDC2 overexpression group were found to be significantly lower than those of the control group." (PMID 38783226, 2024). "In order to further verify whether ECHDC2 overexpression could inhibit the proliferation of GC cells in vivo, we constructed a subcutaneous tumor model in nude mice." (PMID 38783226, 2024). "Given the extensive role of P38 MAPK signaling and MCCC2, this regulation has profound implications, extending beyond glycolysis to potentially affect other cellular processes, suggests that ECHDC2 may have a broader regulatory role in tumor cell metabolism and survival." (PMID 38783226, 2024). "The role of ECHDC2 in GC was further assessed using colony formation assays, CCK8 assay, EDU assay, Glucose and lactic acid assay, and subcutaneous tumor experiments in nude mice." (PMID 38783226, 2024).
cardiovascular diseases (1 paper, 2016). "ECHDC3 shares 30 % identity with ECHDC2, and these proteins may possibly have similar functions in the pathophysiology of cardiovascular diseases." (PMID 27586541, 2016).
ECHDC2 also shares sentences with these, for which no sentence is quoted: cancer (1 paper); gastric cancer (1); glioblastoma (1); gynecologic cancer (1); ovarian carcinoma (1).